SRM (spermidine synthase)
Description:
Catalyzes the production of spermidine from putrescine and decarboxylated S-adenosylmethionine (dcSAM). Has a strong preference for putrescine as substrate, and has very low activity towards 1,3-diaminopropane. Has extremely low activity towards spermidine.
Synonyms: SPDSY; SPS1; SRML1; PAPT
Tractability: Small molecule: a structure with a bound ligand is known; it has a high-quality binding pocket; it belongs to a druggable protein family. PROTAC: ubiquitination databases record sites on it; its protein half-life has been measured; a small molecule that binds it is known.
Target class: Enzyme; Transferase
Gene: Protein-coding gene on chromosome 1 (11,054,584 to 11,060,053, reverse strand). Ensembl gene ENSG00000116649.
Subcellular location (Human Protein Atlas): Nucleoplasm; Cytosol
Pathways (Reactome):
Metabolism: Metabolism of polyamines
Gene Ontology:
Molecular function: identical protein binding; protein binding; protein homodimerization activity; spermidine synthase activity; catalytic activity
Biological process: spermidine biosynthetic process; polyamine metabolic process; polyamine biosynthetic process; spermine biosynthetic process
Cellular component: cytosol
Genetic constraint (gnomAD): Loss-of-function variants: 14 observed, 36.93 expected, observed/expected ratio (o/e) 0.38, 90% interval 0.25 to 0.59. The upper end of that interval is the gene's LOEUF score, 0.59, which puts it in group 2 of 6, group 1 being the genes least tolerant of losing a copy. Missense variants: 244 observed, 377.61 expected, observed/expected ratio (o/e) 0.65, 90% interval 0.58 to 0.72. Synonymous variants: 195 observed, 162 expected, observed/expected ratio (o/e) 1.2, 90% interval 1.07 to 1.36.
Homologues: Orthologues: chimpanzee SRM (99% identical), mouse Srm (95% identical), pig SRM (94% identical), dog SRM (93% identical), guinea pig SRM (92% identical), rat LOC120101528 (87% identical), tropical clawed frog srm (81% identical), zebrafish srm (76% identical), Caenorhabditis elegans spds-1 (57% identical), Drosophila melanogaster SpdS (52% identical). Paralogues in human: SMS (24% identical).
Diseases named in the same sentence as SRM in open-access papers:
SRM is named in the same sentence as 32 diseases in open-access papers, as found by Europe PMC text mining. Sharing a sentence is not in itself a finding about the gene and the disease. The quoted sentences say what the papers report.
colorectal cancer (6 papers, 2016 to 2025). A primary or metastatic malignant neoplasm that affects the colon or rectum. "Besides its impact on adaptive immunity, the production of spermine mediated by spermidine synthase seems to be a determinant of the antitumor effects of tumor-associated macrophages in the progression of colorectal cancer." (PMID 40612676, 2025). "In this regard, it has been reported that SRM gene expression is upregulated in colorectal cancer through the function of lncRNA ELFN1-AS1 and miR-423 sponge which can be a confirmation of our results." (PMID 39028420, 2024). "However, our study is the first to report the putative involvement of SAT1, SMOX, SRM, and RR M2 in colorectal cancer." (PMID 31417867, 2019). "These analyses reveal the unknown effect of SMOX, SMS, and SRM genes in colorectal cancer." (PMID 31417867, 2019). "The results of coexpression analysis coupled to ENCODE ChIP-Seq data strongly suggest c-Myc and C/EBPβ as regulators of the expression of key enzymes of polyamine metabolism that are upregulated in colorectal cancer: SMOX, AZIN1, MTAP, SRM, AMD1, ODC1, and AGMAT." (PMID 27433286, 2016).
prostate carcinoma (6 papers, 2005 to 2025). A carcinoma that arises from epithelial cells of the prostate gland. "SRM is overexpressed in prostate cancer and clear cell renal cell carcinoma (ccRCC), serving as a reliable biomarker and therapeutic target." (PMID 40823069, 2025). "Interesting results were reported on the overexpression of spermidine synthase (SRM) in prostate cancer tissues and miR-1908-mediated regulation of SRM, which controls the secretion of extracellular vesicles (EV) in prostate cancer." (PMID 36091792, 2022). "In prostate cancer (PCa) tissues, the expression level of spermidine synthase (SRM) is elevated." (PMID 35463352, 2022). "On the one hand, we overexpressed SRM in PGC1α-expressing cells to counteract the reduced expression and secretion of this enzyme elicited by the coactivator in PC3 prostate cancer cells." (PMID 40268923, 2025). "We then integrated the results obtained in vitro and with the murine prostate cancer model and identified two proteins consistently altered upon PGC1α perturbation in PCa, ATPase Na + /K+ Transporting Subunit Beta 1 (ATP1B1) and spermidine synthase (SRM)." (PMID 40268923, 2025).
breast carcinoma (4 papers, 2019 to 2025). "Four high-risk independent prognostic factors (OAZ1, SRM, SMOX, and SMS) were validated as being upregulated in breast cancer tissues." (PMID 40823069, 2025). "Paclitaxel treatment elevated intracellular levels of ornithine and total polyamine (including putrescine, spermidine, and spermine), and increased expression of ODC1 and SRM (but not SMS) in breast cancer cell lines." (PMID 39058337, 2024). "High expression of CSNK2B (p = 0.0041, HR = 1.37), GRPEL1 (p = 0.0200, HR = 1.29) and QARS (p = 0.0350, HR = 1.26) were corelated with worse prognosis in breast cancer patients, whereas CCND3, HDAC3, SH3BGRL3, SRM, and UBE2D4 were not correlated with OS." (PMID 31781497, 2019).
malaria (3 papers, 2015 to 2016). Malaria is a serious and sometimes fatal disease caused by a parasite that commonly infects a certain type of mosquito which feeds on humans. "The aminopropyltransferase spermidine synthase (SpdS) is a promising drug target in cancer and in protozoan diseases including malaria." (PMID 27661085, 2016). "In this work, X-ray crystallography was used to examine ligand complexes of spermidine synthase from the malaria parasite Plasmodium falciparum (PfSpdS)." (PMID 25760598, 2015). "In addition, biosynthesis of spermidine and spermine may present potent targets against malaria parasite blood stage parasites, with some preliminary evidence for antimalarial activity of spermidine synthase inhibitors." (PMID 27387533, 2016).
bladder cancer (2 papers, 2023 to 2025). "Overexpression of SRM may increase bladder cancer resistance to pirarubicin, while SRM knockdown improves chemotherapy efficacy." (PMID 40823069, 2025).
gastric cancer (2 papers, 2022 to 2023). A primary or metastatic malignant neoplasm involving the stomach. "Low, or the absence, of correlation between EGFR dependency and expression is shown for CBS and SRM genes in rhabdoid cancer, for the MTR gene in gastric cancer and for the SRM gene in rhabdoid and neuroblastoma cancer cells." (PMID 36361596, 2022).
B cell lymphoma (1 paper, 2021). "It was also showed that inhibition of SRM could slow B cell lymphoma onset in transgenic mice." (PMID 33504899, 2021).
cervical cancer (1 paper, 2023). A primary or metastatic malignant neoplasm involving the cervix. "The intersection of LASSO and SVM-RFE analyses revealed eight hub genes in cervical cancer, which were RBBP4, SRM, GCH1, USP14, TRAIP, CBX4, VEZF1, and TOM1." (PMID 36999051, 2023).
cutaneous leishmaniasis (1 paper, 2022). Leishmaniasis affecting the skin. "infantum for cutaneous leishmaniasis (CL), targeting hypoxanthine-guanine phosphoribosyl transferase (HGPRT) and spermidine synthase (SPDSYN) gene with their species-specific single nucleotide polymorphisms (SNPs)." (PMID 35655325, 2022).
endometrial cancer (1 paper, 2017). Primary or metastatic malignant neoplasm involving the endometrium (mucous membrane that lines the endometrial cavity). "Future studies should explore the role of SAT1, SMS and SRM in the polyamine addiction of endometrial cancer, in particular the mechanisms that cause some of these to be more DFMO sensitive than others." (PMID 29240775, 2017).
hepatoma (1 paper, 2023). "Transcriptome analysis revealed that in Huh7.5 hepatoma cells, the expression of polyamine biosynthesis genes (SRM, SMS, and AMD) was increased, while in hepatocyte-like HepaRG cells, the expression of the SAT1 gene involved in the degradation of spermine and spermidine was increased." (PMID 37189460, 2023).
latent infection (1 paper, 2022). "We observed multiple genes in polyamine pathway, including ODC1, SRM, SMS and DHPS, were significantly dysregulated due to KSHV latent infection." (PMID 35486659, 2022).
liver cancer (1 paper, 2021). An epithelial or non-epithelial malignant neoplasm that arises from the liver. "Spermidine synthase (SRM) is an unfavorable tumor marker that is expressed in renal and liver cancer based on Human Protein Atlas." (PMID 33504899, 2021).
ovarian carcinoma (1 paper, 2022). A malignant neoplasm originating from the surface ovarian epithelium. "SRM knockdown can significantly reduce spermine level in ovarian cancer cells, and targeting polyamines can make ovarian cancer sensitive to immunotherapy." (PMID 36505496, 2022).
prostate tumors (1 paper, 2025). "Consistently with the in vitro and in vivo data, prostate tumors from patients with lower expression of PGC1α presented higher levels of SRM mRNA expression." (PMID 40268923, 2025).
tauopathy (1 paper, 2023). Neurodegenerative disorders involving deposition of abnormal tau protein isoforms (tau proteins) in neurons and glial cells in the brain. "Disruption of polyamine homeostasis has been observed in a mouse model of tauopathy (rTg4510 mice bearing the P301L mutation), specifically upregulated spermidine synthase, as well as increased acetylspermidine (AcSPD) levels." (PMID 36982371, 2023).
tumor (17 papers, 2012 to 2025). "This dual functionality is reminiscent of PGC1α, which exerts non-cell autonomous tumor suppression by regulating secreted factors like spermidine synthase, highlighting the complexity of metabolic regulation in tumor-microenvironment interactions." (PMID 41262299, 2025). "Tumors and normal groups both had high RBBP4 protein levels, and SRM protein levels were moderate in both normal and tumor groups." (PMID 36999051, 2023). "OAT, AGMAT, and SMS are only up-regulated in tumor tissue (Fig. 3a9, a12, a17, b6, b8, and b10), while ODC1 and SRM are highly expressed in tumor and lymphoid tissues (Fig. 3a13, a15, b7, and b9)." (PMID 37164975, 2023). "In the xenograft model, the MC-38 tumour-bearing mice displayed much larger tumours and shorter survival times, whereas additional macrophage-specific SRM transgene abolished this effect." (PMID 27189574, 2016). "Among them, the role of spermidine synthase is aimed to redox regulation of tumor cell followed by anti-cancer treatment." (PMID 23443080, 2012). "Here the authors show that in tumour-associated macrophages ABHD5 inhibits ROS-dependent induction of C/EBPɛ, which transcriptionally activates spermidine synthase, and that blocking ABHD5 delays colorectal cancer growth in mice by inhibiting spermidine production." (PMID 27189574, 2016). "Consequently, the CT-26 or MC-38-inoculated tumours were inhibited by SRM overexpression." (PMID 27189574, 2016). "They found a significant increase in the expression of polyamine-related genes ODC1, SRM, SMS, SAT1, and spermine oxidase in tumour-affected tissues." (PMID 39408925, 2024). "Data analysis showed that the expression of SRM and CPA4 mRNAs in tumor tissue increased compared to the adjacent normal tissue, while the expression of SOX4 mRNA did not change." (PMID 39028420, 2024). "The MIR4435-2HG- and ELFN1-AS1-associated ceRNA subnetworks affected and regulated the expression of the COL5A2, LOX, OSBPL3, PLAU, VCAN, SRM, and E2F1 target genes and were found to be related to prognosis and tumor-infiltrating immune cell types." (PMID 33750326, 2021). "Furthermore, HIF‐1α knockdown significantly decreased tumor‐initiating capacity in vivo, as measured by tumorigenicity assay, which was rescued by overexpression of ODC1 and SRM." (PMID 39058337, 2024). "Aggressive tumor behavior and poor outcome is correlated with high expression of synthetic genes (ODC1, SRM, SMS, AMD1, AZIN1) and low expression of catabolic genes (OAZ1, OAZ2, SAT1, PAOX), and these were identified as direct MYC effects by promoter activity and MYCN binding studies." (PMID 29799508, 2018). "However, a targeted shRNA library screen identified EIF5A, AMD1, SRM, and DHS as tumor suppressors in the Eμ-MYC model." (PMID 29799508, 2018). "Finally, in the sub-networks related to target lncRNAs, the expression levels of SOX4, SRM, and CPA4 (with the highest level of expression change based on bioinformatics analysis) mRNAs, in 32 tumor and 32 normal colorectal tissues, were investigated using qRT-PCR." (PMID 39028420, 2024). "In contrast, upregulation of the biosynthetic activities of polyamine-producing enzymes such as ODC, SRM, SAMDC, and SMS by oncogenic signaling results in increased levels of polyamines, which are thought to play important roles in the maintenance of the transformed phenotype and tumor development." (PMID 32591507, 2020).
cancer (13 papers, 2012 to 2025). A tumor composed of atypical neoplastic, often pleomorphic cells that invade other tissues. "In this work we have shown for the first time, the detection of spermidine synthase (SRM) in the secreted fraction of cancer cells, in both in vitro and in vivo scenarios." (PMID 40268923, 2025). "The study also revealed that the oncogene MYC regulates the transcription of key enzymes involved in polyamine metabolism, including ornithine decarboxylase, spermidine synthase, and spermine oxidase in this type of cancer." (PMID 38187259, 2024). "ODC1, SAT1, SMOX, and SRM genes are known to decrease cell proliferation in several cancer cell lines." (PMID 31417867, 2019). "Moreover, the SRM inhibitors would be a research line for therapy in this subtype of cancer." (PMID 33504899, 2021). "Hence, increase of spermidine synthase in DOXO treated cancer cell may present regulatory response which may increase resistance of cancer cell." (PMID 23443080, 2012). "The expression levels of OAZ1, SMOX, SRM, and SMS were significantly elevated in cancer tissues compared to normal tissues, as confirmed by qRT-PCR, Western blot, and immunohistochemistry." (PMID 40823069, 2025). "We also found the SRM, GAD1 and SMS were significantly elevated in contrast with those in paired normal samples in human cancers." (PMID 38637116, 2024). "In our initial analysis we noted increased expression of ODC1, spermidine synthase (SRM) spermine synthase (SMS) and decreased expression of SAT1 in cancers (n = 176) as compared to normal endometrial samples (n = 12)." (PMID 29240775, 2017). "Altogether, our data strongly suggest that SRM expression and secretion is under negative control of PGC1α and influences the paracrine communication between cancer cells that further sustains cell growth." (PMID 40268923, 2025).
infection (10 papers, 2016 to 2023). The state of being infected such as from the introduction of a foreign agent such as serum, vaccine, antigenic substance or organism. "These clusters included genes encoding chalcone synthase and a spermidine synthase that were specifically and highly expressed after infection with A2-J." (PMID 34122492, 2021). "In order to determine whether the decreased genotoxicity of the ΔspeE mutant is associated with the spermidine synthase SpeE or to spermidine itself, we added increasing concentrations of spermidine in the interaction medium during HeLa cell infection." (PMID 31578245, 2019). "There were two transcripts with low HSP scores to the 10A06 effector of H. schachtii: expression of this gene induces morphological changes in the host, targets spermidine synthase and possibly disrupts Arabidopsis defense signalling leading to increased susceptibility to infection." (PMID 26824923, 2016). "In summary, A2-J infection significantly and specifically up-regulates genes related to cell wall modification and membrane transport, chalcone synthase, and spermidine synthase at an early phase of gall formation." (PMID 34122492, 2021). "Data exploration using GO analysis also revealed higher expression of spermidine synthase activity at 6 h post-infection compared to the control." (PMID 29725322, 2018). "Studies of Leishmania donovani have shown that both ornithine decarboxylase and spermidine synthase, two enzymes of the polyamine biosynthetic pathway, are critical for promastigote proliferation and required for maximum infection in mice." (PMID 27795357, 2017). "In addition to cell wall modification enzymes, infection with A2-J specifically induced the expression of spermidine synthase." (PMID 34122492, 2021). "Furthermore, depletion of polyamines through short hairpin RNA (shRNA) knockdown of spermidine synthase prevents infection with EBOV and MARV in cell culture." (PMID 27460797, 2016). "However, infection with the virulent pathotype of M. arenaria induced the expression of genes that are helpful in forming a feeding site for the nematode; these genes include chalcone synthase, spermidine synthase, and genes related to cell wall modification and transmembrane transport." (PMID 35448735, 2022). "In our study, we found that the expression of ODC1 and SRM were both upregulated in the HBV replication cells and cell models of infection." (PMID 32373551, 2020). "Infection of control water-treated roots resulted in significantly increased expression of spermidine synthase, PqSPD, from 0 to 1dpi, but not from 1 to 6 dpi, and then significantly decreased expression from 6 to 12 dpi, returning to pre-infection levels." (PMID 37447101, 2023). "In contrast, infection with A2-J fails to alter gene expression at 1 DPI, but it does specifically induce the expression of genes encoding chalcone synthase and spermidine synthase, which might suppress lignin synthesis and the SA-mediated defense response." (PMID 34122492, 2021). "Infection with A2-J did not induce statistically significant changes in gene expression within one day post-inoculation (DPI), but afterward, A2-J specifically induced the expression of chalcone synthase, spermidine synthase, and genes related to cell wall modification and transmembrane transport." (PMID 34122492, 2021).
SRM also shares sentences with these, for which no sentence is quoted: neuroblastoma (4 papers); alcohol dependence (2); Alzheimer disease (2); Anxiety (2); dementia (2); depression (2); encephalomyopathy (2); asthma (1); Chagas disease (1); clear cell renal cell carcinoma (1); fungal infection (1); nematode infection (1); rhabdoid cancer (1).